TNF (tumor necrosis factor)
Diseases named in the same sentence as TNF in open-access papers (continued):
Sharing a sentence is not in itself a finding about the gene and the disease.
intracerebral hemorrhage (continued). "Both the presence of intraventricular hemorrhage and intracerebral hemorrhage (ICH) post-aneurysm rupture were associated with elevated CMD IL-6 (p = 0.003) and TNF-a." (PMID 28848487, 2017). "TNF-α was clinically correlated with acute hematoma enlargement, edema development, and poor patient outcome following spontaneous intracerebral hemorrhage (ICH)." (PMID 24285977, 2013). "In addition, the effects of Cory on microglia activation and TNF-α secretion were better than those of rapamycin, which has been reported to suppress microglial activation and TNF-α expression induced by intracerebral hemorrhage." (PMID 33927622, 2021). "TNFα levels greater than 1.40 pg/ml were associated with a 4.1-fold increase in mortality, and this together with CAR being correlated with increased hemorrhage size and ICH score further demonstrate the inflammatory consequences after intracerebral hemorrhage." (PMID 33585095, 2021). "Interestingly, HBOT preconditioning has been observed to reduce and even prevent aberrant inflammation by lowering neurotoxicity microglia activity, TNF-α expression, and neuronal degeneration, resulting in improvement in motor function after intracerebral hemorrhage." (PMID 32899709, 2020). "In the mice intracerebral hemorrhage model, a lesion similar to SCI, hAMSC treatment had suppressed TNFα expression in the damaged site." (PMID 39324071, 2024). "Several clinical studies suggest that serum inflammatory factors such as IL‐6, TNF‐α, and hs‐CRP released after intracerebral hemorrhage are closely related to brain edema and brain injury." (PMID 32533644, 2020). "Future studies directed at lowering CRP, TNFα, and Hcy and/or increasing VEGF in intracerebral hemorrhage patients are needed and may be beneficial." (PMID 33585095, 2021). "This current study looks to expand on our prior results and will look at the relationship between tumor necrosis factor alpha (TNFα), C-reactive protein (CRP), VEGF, Homocysteine (Hcy), and CRP to albumin ratio (CAR) in predicting outcomes and severity in spontaneous intracerebral hemorrhage." (PMID 33585095, 2021). "In the development of intracerebral hemorrhages, the expression of Toll-like receptor 4 (TLR4) is enhanced, and this could lead to an increase in the levels of TNF-α, IL-6, and IL-1β through the TLR4/NF-κB pathway, followed by aggravation of brain lesions." (PMID 33133217, 2020). "In this sense, it has been reported that endothelial progenitor cells improved the neurological function of rats with intracerebral hemorrhage by decreasing pro-inflammatory cytokines such as IFN-γ, IL-6, and TNFα, and increasing anti-inflammatory cytokines such as TGFβ1 and IL-10." (PMID 29720269, 2018). "In a rat model of intracerebral hemorrhage, CGS21680 administered directly into the striatum immediately prior to the induction of intracerebral hemorrhage reduces parenchymal neutrophile infiltration and tissue damage: an effect that might be mediated by inhibition of TNF-α expression." (PMID 25165414, 2014).
Osteopenia (44 papers, 2009 to 2025). Osteopenia is a term to define bone density that is not normal but also not as low as osteoporosis. "Elevation of Receptor Activator of Nuclear factor Kappa- β Ligand (RANKL) in bone marrow and synovial tissues (caused by IL- β1 and TNF-α) increases osteoclast differentiation resulting in pathological bone resorption and osteopaenia." (PMID 35321113, 2022). "Accordingly, to counteract the MSC dysfunction and osteopenia induced by mechanical unloading, rapamycin inhibition of mTOR signaling functions as a downstream therapeutic to protect against TNFα deficiency." (PMID 33384406, 2021). "TNFα is an interesting cytokine in regard to systemic inflammation because it is linked to extrapulmonary manifestations of COPD such as osteopenia and muscle wasting." (PMID 21896197, 2011). "Moreover, the induction of hemarthrosis led to increased levels of TNF-α in the affected joints of FVIII-deficient mice, and the inactivation of TNF-α or iRhom2 reduced synovial inflammation and osteopenia in this mouse model for HA." (PMID 31261789, 2019). "Disuse osteopenia, periprosthetic and infection related bone loss are all associated with increases in 'pathological' osteoblast apoptosis, enhanced cell suicide mediated by proinflammatory cytokines such as TNF alpha, anti CD 95-IgM, Il-1β and Il-6." (PMID 19527527, 2009). "The possible explanation for the relationship between BMD and the incidence of HF in males can be due to the intense inflammation and high cytokine levels such as IL-6, TNF-α, and oxLDL that accompany the osteopenia in males." (PMID 38740674, 2024). "We also evaluated the effects of activity on generalized osteopenia in the subchondral region of the femur, which has been demonstrated to exhibit a differential response to TNF compared to the articular surfaces of bone." (PMID 36732826, 2023). "In bone, most inflammatory factors (such as TNF-α, IL-1, and IL-6) can promote the function of osteoclasts, thus breaking the balance between bone formation and absorption, resulting in osteopenia." (PMID 35923245, 2022). "TNF-α was also significantly higher in the osteopenia group with a median of 1.9 (1.4-2.6) as compared to the control group with a of median 1.6 (1.1-2.3) (p = 0.032)." (PMID 33376557, 2020). "This has a relevance to inflammation-associated osteopenia, which is associated with a downregulation of LOX in response to tumor necrosis factor alpha (TNFα)." (PMID 25978957, 2015). "The normal levels of serum IL-1, IL-8, and TNF-α in our study in cirrhotic patients with osteopenia compared to the controls indicated that these cytokines do not play a role in the pathogenesis of hepatic osteodystrophy." (PMID 23097664, 2012). "No changes were observed between Rsk2−/y without TNFα overexpression, and controls, consistent with other studies showing that osteopenia associated with Rsk2 loss, tends to occur later." (PMID 40140815, 2025). "Our study also demonstrated that there was a strong correlation between the timing of anti-TNF therapy and body composition components, especially bone mineral content, suggesting that delaying anti-TNF therapy may increase the possibility of osteopenia." (PMID 36824176, 2023). "Together, the data suggest that osteopenia during M. avium infection requires both IFNγ and TNFα." (PMID 37153579, 2023). "Moreover, the level of the inflammatory factor TNF-α was significantly higher in the osteopenia group than in the control group." (PMID 36032115, 2022). "TNF-α, IL-1, and IL-6 also suppress differentiation of osteoblasts, which is consistent with our observation that osteoblast numbers were reduced in bones which exhibited osteopenia." (PMID 27956598, 2017). "We propose that down-regulation of lysyl oxidase in pluripotent cells by TNF-α in inflammatory diseases can lead to a smaller pool of precursor cells ultimately leading to a diminished population of bone or cartilage producing cells, and consequent osteopenia." (PMID 24971753, 2014).
Osteopenia (continued). "Furthermore, excess GAG deposition may lead to activation of TLR-4 triggering TNF-α production and prostaglandin E2, leading to pain and osteopenia, inflammation and macrophage activation." (PMID 35321113, 2022). "Furthermore, in hemophilic mice subjected to intra-articular bleeding, treatment with etanercept to block TNF-α reduced synovial inflammation and largely prevented the activation of osteoclasts and the resulting osteopenia in the trabecular bone adjacent to the hemarthrosis." (PMID 31261789, 2019). "Moreover, studies have reported that TNF-α antibodies can decrease systemic bone loss and increase bone mineral density indicating that anti-TNF-α can be used against systemic osteoporosis and osteopenia." (PMID 26065006, 2015). "Salvianolate treatment ameliorate osteopenia and improved bone quality through increasing the Osterix, OPN, Runx2 level and decrease TNF-α, IL-6 level in serum." (PMID 36387862, 2022). "Tumor necrosis factor-α (TNF-α) has been reported to be involved in nontumor-induced osteopenia as well as in stimulating bone resorption and inhibiting bone formation." (PMID 35788217, 2022). "Salvianolate treatment could increase Osterix, OPN, Runx2 level and decrease TNF-α, IL-6 level in serum and IL-1β protein in TNF-α-induced MC3T3-E1 osteoblasts, finally ameliorate osteopenia and improved bone quality." (PMID 36387862, 2022). "Additionally, it is well documented that the production of local and circulating pro-inflammatory cytokines, including TNF-α, IL6, and IL10, plays an important role in the occurrence and development of osteopenia by inhibiting osteoblast function and promoting osteoclast differentiation." (PMID 30819183, 2019). "Tumor necrosis factor-α (TNF-α) is involved in tumor-induced bone resorption and non-tumor-induced osteopenia." (PMID 33800689, 2021).
retinal degeneration (44 papers, 2008 to 2025). Degeneration of the retina. "Remarkably, TNF signaling, associated with ocular inflammatory diseases and retinal degeneration, is highly activated in RD mice." (PMID 34777465, 2021). "Several cytokines and chemokines including MIP-1α (CCL3), MIP-1β (CCL4), MCP-1 (CCL2), MCP-3 (CCL7), TNF-α, IL-1β and IL-6 have been implicated in photoreceptor-microglial crosstalk and retinal degeneration." (PMID 27814376, 2016). "Chronic inflammatory mediators such as interleukin-6 (IL-6) and tumor necrosis factor-alpha (TNF-α) further promote retinal degeneration and angiogenesis." (PMID 40507504, 2025). "Intravitreal and intraperitoneal injections of Adalimumab prevent retinal degeneration and photoreceptor cell death by preventing TNF-α upregulation and reducing inflammation, oxidative stress, and apoptosis." (PMID 35576057, 2022). "miR-155 was identified to potentially act in a positive-feedback loop with pro-inflammatory cytokines including TNF-α, propagating MP-mediated inflammation and subsequent retinal degeneration." (PMID 33037565, 2021). "In this study, we first analysed the early stages of retinal degeneration and the profile of TNFα expression in rd10 mice under our housing conditions." (PMID 26170250, 2015). "Nevertheless, to our knowledge, we present the first study that evaluates the effect of TNFα inhibitors on the progression of the retinal degeneration in a murine model of RP." (PMID 26170250, 2015). "Apoptosis of photoreceptor cells is a common feature of retinal degeneration, and a variety of stimuli, such as tumor necrosis factor (TNF), Fas ligands (FasL), mitochondria, and ER stress, can lead to cell death." (PMID 26137316, 2015). "Our current study demonstrated that retinal degeneration accompanied by upregulation of TNFα and IL-6, GFAP and oxidative damage was ameliorated by blocking TNFα with Infliximab." (PMID 25301432, 2014). "Based on previous studies we decided to evaluate the potential protective effect of the blockade of TNFα in an experimental porcine model of retinal degeneration." (PMID 25301432, 2014). "TNFα is involved in retinal degeneration through caspase-3 activation, caspase-independent mechanisms and reactive gliosis." (PMID 25301432, 2014). "Our study suggests that TNFα is playing an important role in cell death in an ex vivo model of retinal degeneration by activating different cell pathways at different cell layers of the retina that should be further studied." (PMID 25301432, 2014). "In summary, our results corroborate that RP patients have ocular inflammation and that TNFα plays an important role in the retinal degeneration induced by PDE6 inhibition in cultured porcine retinas." (PMID 25301432, 2014). "The role of TNFα in photoreceptor degeneration and the possible therapeutic use of antibodies against TNFα in the treatment of RP or other retinal degenerations remain quite unexplored." (PMID 25301432, 2014). "We also observed that pharmacological inhibition of TNFα with Infliximab, a specific monoclonal antibody against TNFα, prevented retinal degeneration in cultures of porcine retina exposed to Zaprinast." (PMID 25301432, 2014). "TNFα also plays a significant role in various intraocular diseases such as uveitis, glaucoma, and retinal degenerations." (PMID 23687426, 2013). "TNFα in the vitreous is elevated during retinal degeneration and TNFα blockers protect photoreceptors from degeneration in a retinal detachment model." (PMID 22615780, 2012). "Furthermore, its anti-inflammatory and antioxidant properties suppress proinflammatory cytokines (e.g., IL-6, TNF-α) and oxidative stress, both of which contribute to retinal degeneration." (PMID 41293731, 2025). "The NaIO3-induced retinal degeneration mock group showed increased expression of Fas, inflammatory cytokines (TNF-α, IL-6, and IL-1β), MCP-1, and macrophages (F4/80), and an elevated M1 (CD11c)/M2 (CD206) macrophage ratio compared with that in the normal mouse group." (PMID 38534392, 2024).
retinal degeneration (continued). "Also, monoclonal anti-TNFα antibodies prevented retinal degeneration in a murine model of retinitis pigmentosa." (PMID 38536827, 2024). "In addition, we showed that the use of antibodies against TNFα ameliorated retinal degeneration and downregulated NLRP3 inflammasome components." (PMID 36670960, 2022). "Although we identified apoptosis and necroptosis using staurosporine, which is not a physiological agonist, necroptosis is strongly linked to tumour necrosis factor-α (TNF-α) signalling, and aberrant TNF-α signalling has been extensively linked to retinal degeneration and AMD." (PMID 25735751, 2015). "It is tempting to speculate that Adalimumab or other anti-TNFα agents could be a promising therapy for RP and other retinal degenerations." (PMID 26170250, 2015). "Therefore, we studied the effect of Adalimumab, a monoclonal antibody against TNFα, on the progression of the retinal degeneration at this age." (PMID 26170250, 2015). "The results obtained in the present study revealed that intraperitoneal administration of Adalimumab, a recombinant human monoclonal antibody against TNFα, reduced retinal degeneration decreasing photoreceptor cell death and reactive gliosis at early stages of RP in rd10 mice." (PMID 26170250, 2015). "Therefore, we analysed gene expression of TNFα during the time course of retinal degeneration in our housing conditions." (PMID 26170250, 2015). "We tested whether incubation with 2 μg/mL Infliximab, a TNFα blocker, for 24 hours prevented Zaprinast-induced retinal degeneration." (PMID 25301432, 2014). "We studied whether Zaprinast-induced retinal degeneration was accompanied by altered glial reactivity, and if it was the case, whether the blockade of TNFα could prevent it." (PMID 25301432, 2014). "Our finding suggests that the increased number of AF spots is related to resident microglia proliferation, which established a cytokine milieu that was skewed to inflammation by upregulating the expression of the IL-1β, IL-6 and TNFα genes, which subsequently accelerated retinal degeneration." (PMID 23828046, 2013). "Therefore, adalimumab considerably diminished TNFα-induced reactive gliosis and retinal degeneration during culture." (PMID 23687426, 2013). "In addition, resident microglia can proliferate and produce high levels of TNFα and IL-1β, which subsequently lead to the acceleration of retinal degeneration." (PMID 23828046, 2013). "Impaired migratory ability, reduced phagocytic function and excessive NO and TNF-α production in myeloid-derived cells in these genetically modified mice may alter the local para-inflammatory response resulting in more severe retinal degeneration." (PMID 21850237, 2011). "It was shown that NF-κB is activated in rd mice and light-induced retinal degeneration Interestingly, GSK3β was shown to facilitate NF-κB transactivation by TNF-α since GSK3β deficient mouse embryonic fibroblasts exhibit defective NF-κB activation in response to TNFα." (PMID 36139472, 2022). "The aims of this study were to corroborate the presence of high TNFα concentration in the eyes of RP patients and to evaluate whether the blockade of TNFα with Infliximab, a monoclonal anti-TNFα antibody, prevented retinal degeneration induced by PDE6 inhibition in cultures of porcine retina." (PMID 25301432, 2014). "Thus, the data presented here suggest that adalimumab is an effective agent for decreasing glial cell modifications and retinal degeneration induced by TNFα, and therefore may represent a novel way to control retinal gliosis." (PMID 23687426, 2013). "Furthermore, the persistent gliosis and gliotic scar formation in Cdc42-KD mice may also be detrimental and contribute to retinal degeneration through the secretion of pro-inflammatory cytokines such as TNFα and CCL2." (PMID 23372671, 2013).
retinal degeneration (continued). "A study showed that activation of NF-κB may be associated with photoreceptor cell death through upregulation of gene expression of proinflammatory and neurotoxic molecules (e.g., tumor necrosis factor α) in microglial cells in the retinal degeneration (rd) retina." (PMID 22876136, 2012). "Key inflammatory mediators such as tumor necrosis factor-alpha (TNF-α), interleukins (IL-6, IL-1β), and activated microglia contribute to retinal degeneration." (PMID 40428167, 2025). "A significant increase in mRNA levels for TNF-α, IL-1ß and MCP-1 was found in retinal degeneration rats." (PMID 24349184, 2013). "Although the immune response is a late event in other models of retinal degeneration, our results clearly showed that CPA induced a significant decrease of Iba 1 reactive microglial cell population, and a decrease of iNOS and TNF α mRNAs in this model of light induced retinal degeneration." (PMID 29912966, 2018). "In comparison with normal controls, the mRNA levels of pro-inflammatory cytokines, including IL-1β, IL-6, TNF-α, and MCP-1 increased significantly higher in the MNU group (p < .01; n = 8), indicating that inflammation was involved in the pathogenesis of retina degeneration." (PMID 33501868, 2021). "Release of soluble factors by activated microglia and Müller cells such as the proinflammatory cytokines TNF and monocyte chemoattractant protein MCP-1, which are thought to contribute to retinal degeneration in diabetic and other retinopathies, may contribute to the retinal pathology." (PMID 27765056, 2016).